KRAS (KRas proto-oncogene, GTPase)
Diseases named in the same sentence as KRAS in open-access papers (continued):
Sharing a sentence is not in itself a finding about the gene and the disease.
cancer (continued). "The consequences of our findings may have broad implications for T cell recognition of HLA-C beyond the specific example of KRAS-G12D recognition in cancer." (PMID 35587797, 2022). "The identification of the differentially-expressed lncRNAs with crucial roles in regulating the potential cancer-related pathways may provide reference lncRNAs for diagnosing and treating KRAS mutant CRC." (PMID 35562390, 2022). "Remarkably, PLK1 and XPO1 have been reported to be selectively required for KRAS-mutant cancers by counteracting mitotic and nuclear export stress associated with KRAS-induced tumorigenesis, and our recent study has implicated PLK1 in metabolic stress response of KRAS-mutant cancers." (PMID 35039048, 2022). "KRAS may be a reliable prognostic biomarker in the diagnosis of cancer patients and has the potential to be included in cancer-targeted drugs." (PMID 36330448, 2022). "Thus, the D-VC and ATO combination shows a promising path to treat KRAS-mutant cancers in clinical settings." (PMID 36359850, 2022). "In addition, next-generation KRAS small-molecule inhibitors are making their way into clinics, either as monotherapy or in combination with other therapies, and these developments provide an alternative highway to fight hard-to-treat KRAS-driven cancers." (PMID 35014625, 2022). "The RAS proteins HRAS, KRAS, and NRAS (H, K, NRAS) are RAS oncoproteins that cause human cancers." (PMID 35409064, 2022). "Based on the uptake inhibition induced by EIPA (a Na+/H+ exchange blocker used as a specific inhibitor of macropinocytosis), a variety of delivery systems have been identified, of which macropinocytosis is the dominant internalization mechanism in KRAS mt cancer cells." (PMID 35154489, 2022). "In recent years, major steps have been taken in the battle against mutant KRAS–driven cancers." (PMID 35014625, 2022). "KRAS‐mutant cancer cells modulate the properties of CAFs, endothelial cells, and ECM composition." (PMID 35791509, 2022). "Despite potential toxicological challenges as ribosome biogenesis is also an important physiological process, modulation of NOP56 activity may afford a therapeutic window for targeted inhibition of mTOR in KRAS-mutant cancers." (PMID 35039048, 2022). "They showed effectiveness in KRAS-driven cancers when combined with MEK inhibitors (trametinib)." (PMID 36077640, 2022). "Consequently, identification of new targets for innovative treatment strategies tailored to KRAS-mutant cancers still represents a pressing need." (PMID 35039048, 2022). "Is there a therapeutic window for macropinocytosis-based treatments against KRAS mutant cancer?" (PMID 35154489, 2022). "With efforts to develop compounds for each KRAS mutation, cancers that harbor aberrant KRAS signaling in the absence of a protein mutation have still not been addressed." (PMID 36011352, 2022). "This approach offered an effective lead degrader for the treatment of KRAS-mutant cancer." (PMID 35680848, 2022). "In the present study, we investigated the function of NOP56 in KRAS-mutant cancers." (PMID 35039048, 2022). "Since the attempt at the allosteric inhibition of KRAS encountered difficulties, research efforts have turned towards the displacement of KRAS from the plasma membrane, the inhibition of downward signaling molecules, and the percussion of the cancer cell’s metabolic repertoire." (PMID 35408980, 2022). "Because KRAS alterations are implicated in a broad spectrum of human malignancies, our findings may also be applicable to other lineages of cancer with high frequencies of KRAS alterations." (PMID 35039048, 2022). "In this retrospective cohort study, we extracted the clinical, molecular, and pathologic data from the electronic health records of patients with advanced KRAS-mutant NSCLC at Shandong Cancer Hospital between January 2018 and May 2022." (PMID 36741723, 2022). "Only in KRAS-mut cancers was a single family member, ADAMTS8, conserved." (PMID 36612014, 2022).
cancer (continued). "Taking into account that KRAS G12C occurs in numerous cancer types, such as lung, colorectal, and cervical adenocarcinomas, this class of agents brings a unique therapeutic opportunity to treat KRAS G12C-driven cancers." (PMID 35177674, 2022). "GJB6 was conserved only in EGFR-mut and KRAS-mut cancers while the latter also conserved GJB3." (PMID 36612014, 2022). "However, when the inhibitor was combined with si-KRAS, this resulted in a synergistic anti-cancer effect in both ovarian OSE cell lines and allograft OC model impeding cell proliferation and migration and also inducing apoptosis in tumorsin vivo." (PMID 36451660, 2022). "Kirsten rat sarcoma (KRAS) is the most frequent isoform in the RAS family, the most common oncogene family in human cancer, and KRAS accounts for approximately 85% of mutations in RAS-mutant cancer." (PMID 36508072, 2022). "in 2011, reported activated oncogene HRAS or KRAS could increase basal autophagy which was essential to maintain human cancer cell survival in starvation and in oncogenesis." (PMID 36263211, 2022). "Inhibiting KRas directly in these cancers has proved to be difficult–suggesting that it might be wiser to attack KRas signals indirectly." (PMID 36269753, 2022). "Notably, inhibition of xCT selectively kills KRAS-mutant cancer cells in vitro and strongly attenuates oncogenic RAS transformation in xenograft models, highlighting an unappreciated function of the antioxidant program to RAS-driven tumourigenesis." (PMID 36338517, 2022). "Thus, the bias of specific cancers towards distinct KRAS mutations could arise from potential tissue-specific differences of normal cells in the mutagenic process or repair capacity and/or in their responses to the nature of the signaling imparted by specific KRAS mutations." (PMID 36069770, 2022). "We next examined the potential reason why KRAS is aberrantly expressed in diverse cancer types." (PMID 35563733, 2022). "Although some of the described novel therapies show promising results, it is evident that the drug resistance is a common feature of KRAS-mutant cancers that will be a most challenging task to overcome, making it a critical limiting factor in eradication of highly malignant cancers." (PMID 36359850, 2022). "The genetically engineered VV, Pexa-Vec (JX-594), targets cancer cells via multiple mechanisms, whereby virus replication is activated by EGFR/KRAS pathway signaling, cellular thymidine kinase (TK) levels, and resistance to type I interferons (IFNs) in cancer cells." (PMID 36221123, 2022). "Mutated KRAS is associated with radioresistance in NSCLC and other cancers." (PMID 36591457, 2022). "Therefore, a combination of the cancer targeting therapies with the focus to obtain a potent killing of KRAS-mutant cancer cells will be most effective, if a synergistic potentiation in the drug action outcomes can be realized." (PMID 36359850, 2022). "Hence, downregulation of S6K by the combination of selinexor and KRAS G12C inhibitors can result in suppression of cancer cell growth." (PMID 35573474, 2022). "KRAS mutation was captured in a subtype_I sample (GBC1), paralleling the GSVA findings, reminiscent of the role of KRAS mutation in the gallbladder metaplasia-cancer sequence." (PMID 36198671, 2022). "YAP1 rescues KRAS suppression in KRAS-dependent cancer cells." (PMID 35883668, 2022). "To investigate this hypothesis, we generated cancer lines conditionally expressing oncogenic forms of MET effectors KRAS, PI3K, and STAT3 (p20-KRASG12D, p20-PIK3CAE545A, and p20-STAT3A662C_N664C)." (PMID 35326531, 2022).
cancer (continued). "Moreover, berberine and coptisine significantly stall the Taq DNA polymerase synthesis of DNAs and lower the KRAS mRNA levels in cancer cells." (PMID 36224201, 2022). "Three genes, including Kirsten rat sarcoma viral oncogene (KRAS), Harvey rat sarcoma viral oncogene (HRAS) along with Neuroblastoma rat sarcoma viral oncogene (NRAS), are members of the RAS family, which are associated with cancers." (PMID 35517800, 2022). "It would not be surprising that mitochondrial inhibitors reduced the growth of KRAS mutant cancers." (PMID 35372044, 2022). "Likewise, statin inhibition of KRAS specifically promotes immunogenic cell death specifically of KRAS mutant cancer cells." (PMID 35884561, 2022). "These inhibitors have shown promise in treating different types of cancer, but like nearly all other therapeutic drug candidates that have been used to inhibit KRAS, or effectors of KRAS (i.e., the RAF-MEK-ERK1/2 and PI3K-AKT signaling pathways), acquired resistance continues to be a major problem." (PMID 36581205, 2022). "Specifically, this continuous activation confers to cancer cells the ability to grow in lower glucose concentrations than those required for the growth of normal cells or cancer cells that do not have KRAS mutations." (PMID 36077640, 2022). "The new investigation might be a promising therapeutic approach for KRAS-dependent cancer treatment." (PMID 35409064, 2022). "Many studies have shown that KRAS has an essential relationship with the occurrence of cancer." (PMID 36330448, 2022). "In CRC, KRAS is the most frequent isoform mutation, accounting for about 20% of all human cancers, while neuroblastoma rat sarcoma (NRAS) and Harvey rat sarcoma (HRAS) mutations are found in about 8% and 3% of cancers, respectively." (PMID 35454852, 2022). "Furthermore, KRAS wild-type pancreas cancers are through to arise from distinct oncogenic processes and potentially display unique therapeutic vulnerabilities, warranting closer study." (PMID 35617275, 2022). "RAS genes (KRAS, HRAS, and NRAS) are the most frequently mutated oncogenes in human cancers." (PMID 36291140, 2022). "In addition, mitochondria-associated genes were identified to be essential for survival of KRAS-mutant cancer cells." (PMID 35372044, 2022). "This shows an extremely specialized cell death in KRAS mutant cancers." (PMID 35884561, 2022). "Furthermore, berberine and coptisine significantly stalled the Taq DNA polymerase synthesis of the complementary strand DNAs and lowered the KRAS mRNA levels in cancer cells." (PMID 36224201, 2022). "Moreover, mutant KRAS induces an intrinsic IFN-stimulated gene (ISG) signature that is often seen across many different cancers." (PMID 35858545, 2022). "Vitamin C gets inside these cancer cells and disrupts the expression of KRAS or BRAF genes." (PMID 36245983, 2022). "In order to evaluate if oncogenic KRAS signaling extended to the outside of the cancer cells affecting the properties of the fibroblasts, we evaluated the fibroblast activation state in response to cancer cell-secreted factors." (PMID 36010567, 2022). "To test whether BCL6 induction creates an actionable vulnerability, we treated KRAS-mutant cancer cells with BCL6 chemical inhibitors." (PMID 36377663, 2022). "Different strategies have been applied to overcome chemotherapy resistance in KRAS mutant cancers." (PMID 35705962, 2022).
cancer (continued). "Besides chemical inhibitors, new therapeutics targeting KRAS mutant cancers include exosome-delivered KRAS siRNA (iExosome), mRNA vaccines, anti-KRAS T cell transfer, and cell-permeable RAS antibodies." (PMID 36230914, 2022). "Thus, SBT-100 is a “First-in-Class” anticancer agent for targeting STAT3 and KRAS simultaneously in cancers and provides proof of concept for this novel approach to treating cancer and other diseases by focusing on aberrant intracellular targets." (PMID 35886918, 2022). "This was demonstrated by the application of the integrative analysis of phosphoproteome and drug sensitivity generated for a group of KRAS-mutant cancer cell lines with distinct biological, clinical, and therapeutic characteristics, representative of tumors with the poorest prognosis." (PMID 35495127, 2022). "To further validate that RAS84 expression could predict high RAS activity in RAS mutants in individual cancers, we looked at pan-RAS mutation (KRAS, NRAS, HRAS) distributions across RI values per cohort." (PMID 36163168, 2022). "Increased KRAS activity leads to uninhibited cell growth and proliferation in cancer." (PMID 35954441, 2022). "The detection or testing for KRAS and BRAF gene mutation presents a blueprint and change to standard diagnostic guidelines for inpatient care and creates a major development in early decision-making in personalizing cancer care." (PMID 35782059, 2022). "Our results suggest that canakinumab might be selectively effective against KRAS-mutant cancers and warrant an a posteriori analysis of CANTOS results with respect to KRAS mutation status." (PMID 35327394, 2022). "PPRH selectively suppressed proliferation in KRAS dependent cancer cells." (PMID 35216221, 2022). "KRAS mutations not only cause cell autonomous proliferation and survival of cancer cells but also impact on the lung TME phenotype by non-cell autonomous modulation of immune cells." (PMID 36074553, 2022). "AKT1 was regarded as the major regulator in metabolism of cancer growth and KRAS could promote autophagy under metabolic stress." (PMID 35096270, 2022). "An EGFR-mut cancer cell with its concomitant co-adaptations may find itself greatly disadvantaged within the tumor microenvironment of a KRAS-mut cancer and vice-versa." (PMID 35061724, 2022). "Besides, Kirsten rat sarcoma viral oncogene homolog (KRAS) regard as the most lethal cancer-related proteins takes a crucial role in human aggressive cancers." (PMID 35422861, 2022). "Thus, IRE1α-mediated UPR activates mTOR, which provides a survival signal for NOP56 KD KRAS-mutant cancer cells; conversely, mTOR inhibition leads to overwhelmed UPR and promotes apoptotic cell death by activating the JNK-FOXO3A-BIM axis." (PMID 35039048, 2022). "Mutations in oncogenes such as KRAS and EGFR cause a high proportion oflung cancers." (PMID 35930804, 2022). "SW480 is an EGFR-driven cancer cell and harboring KRAS mutant (G12V) instead of G12S in A549." (PMID 35578244, 2022). "Furthermore, our results show that in some contexts, fibroblast-derived external stimuli can modulate the cancer cell proteome in a way that counteract KRAS-inhibition and support cancer cell-malignant features." (PMID 35805073, 2022). "It is well established in NSCLC, CRC and other solid tumors that responses to KRAS inhibitors are variable; combination strategies in development will depend on characterization of the diverse genomic landscape of KRAS mutant cancers both pre-treatment and upon acquired resistance to therapies." (PMID 36494601, 2022). "The predominantly mutated genes involved in this pathway, i.e., KRAS, BRAF and NF1, were found mutated in 26.05%, 17.06% and 13.06% of RTK-RAS perturbed cases respectively, while additional mutations in all cancer-related receptor tyrosine kinase-encoding genes represented 33.2% of all mutations." (PMID 35158934, 2022). "KRAS is considered to be closely related to various cancers." (PMID 35631410, 2022).
cancer (continued). "Following that, we investigated the DNA methylation level and the upstream regulators of KRAS, such as transcription factors and microRNAs, which could help us understand the aberrant level of KRAS in diverse cancers." (PMID 35563733, 2022). "Collectively, these results indicated that coptisine and berberine could inhibit the KRAS oncogene transcription levels and the proliferation of the cancer cells, suggesting they are promising KRAS-G4 targeting drugs." (PMID 36224201, 2022). "Therefore, further investigation of the oncogenic potential of high KRAS and DX2 levels would help to validate the significance of DX2-targeting therapeutics against KRAS-driven cancers." (PMID 35546148, 2022). "Moreover, our results uncover a reciprocal interaction of NOP56 and mTOR signaling and suggest that combined inhibition of NOP56/mTOR is a rational strategy to combat KRAS-mutant cancer." (PMID 35039048, 2022). "Next, we examined the prognostic value of KRAS in various cancers." (PMID 35563733, 2022). "To gain a better knowledge of KRAS, we first examined KRAS expression in a variety of cancers." (PMID 35563733, 2022). "These new therapy regimens enable KRAS-driven cancers to be fought in various ways." (PMID 35014625, 2022). "Pan-KRAS drugs have also the potential to address a broad range of patient populations, including KRAS G12D-, KRAS G12V-, KRAS G13D-, KRAS G12R-, and KRAS G12A-mutant or KRAS wild-type-amplified cancers, as well as cancers with acquired resistance to KRAS G12C inhibitors." (PMID 35406400, 2022). "Our study suggested that KRAS may be a promising prognostic biomarker for cancer diagnosis and treatment." (PMID 36330448, 2022). "Moreover, the combination with SHP2 inhibitors offers an appealing approach to treat both RTK-activated and KRAS/BRAF-mutant cancers." (PMID 35462913, 2022). "Many studies over the years described the role of mutant KRAS in cancer progression, which might be expected to affect patient survival." (PMID 36163168, 2022). "In addition, we found that they also enriched pro-cancer gene sets: KRAS signaling up, PI3K/AKT/MTOR signaling, and apical surface gene sets." (PMID 35945417, 2022). "Yet, the frequencies of KRAS activation vary dramatically between cancer types." (PMID 34951114, 2022). "Targeting MEK is still an attractive therapy in the treatment of patients with KRAS-mutant cancers." (PMID 35806187, 2022). "We split the data into two groups according to the median level of KRAS and observed that some important signatures (EMT, apoptosis, and TNFα/NFκB signaling) and immune cell infiltration were inclusively enriched in the KRAS-high vs KRAS-low datasets in these cancers." (PMID 35563733, 2022). "Further research showed that growth factors, cancer-associated mutations (KRAS, mutated APC), or cancer-related transcription factors (cMYC) could up-regulate HMGA1 in specific contexts." (PMID 35805937, 2022). "Consequently, the next step to elicit clinically meaningful responses in oncogenic KRAS–driven cancers is to find the safest and the most efficient combinations of drug and therapy regimens based on the genetic background of the patient." (PMID 35014625, 2022). "Therefore, the KRAS-mutation protein has become a focus of drug development for the treatment of KRAS mutant cancers." (PMID 36430323, 2022).